NLRC4 (NLR family CARD domain containing 4)
Diseases named in the same sentence as NLRC4 in open-access papers (continued):
Sharing a sentence is not in itself a finding about the gene and the disease.
Sepsis (continued). "In this study, NLRC4 was highly expressed in all patients with sepsis; therefore, it is reasonable to believe that NLRC4 may cause pyroptosis by activating caspase-1 and promoting the inflammatory response, which consequently leads to the development of sepsis." (PMID 36765335, 2023). "As a result, NLRC4 may be considered a potential therapeutic target of sepsis for further research." (PMID 36765335, 2023). "It is tempting to speculate that NLRP3 activation can complement inefficient NAIP/NLRC4 activation in human macrophages under certain conditions, for example in sepsis when LPS levels are high, as our mRNA expression data suggests NLRC4 expression is lowered under these conditions." (PMID 33380493, 2021). "The results showed that the expression of NLRC4, S100A9 and TXN was significantly higher in sepsis patients." (PMID 40028203, 2025). "The machine learning algorithm screened three PCD-related genes, NLRC4, TXN and S100A9, as potential biomarkers for sepsis." (PMID 40028203, 2025). "In conclusion, this research proposed three programmed cell death related genes (NLRC4, TXN, S100A9) as practical biomarkers for sepsis patients." (PMID 40028203, 2025). "Our findings elucidate a molecular mechanism of ARF in sepsis and contribute to an enhanced understanding of the (patho)physiological role of the NAIP/NLRC4 inflammasome." (PMID 40158217, 2025). "In the validation datasets of GSE28750, GSE57065, GSE13904, GSE26378 and GSE26440, the expression of NLRC4, S100A9 and TXN were also significantly higher in the sepsis group." (PMID 40028203, 2025). "Eight genes (CLEC5A, MALT1, NAIP, NLRC4, SERPINB1, SIRT1, STAT3, and TLR2) related to sepsis diagnosis were screened by multiple machine learning algorithms." (PMID 36817458, 2023). "The qRT-PCR results showed that the expression of CHMP7 was downregulated, while NLRC4 and PLCG1 expression was upregulated in H9C2 cells stimulated with LPS to mimic in vitro sepsis model." (PMID 37939116, 2023). "Our results showed the expression of AIM2, CASP4, NLRC4, and PYCARD was higher and the expression of PVJK and PLCG1 was lower in both sepsis and septic shock patients than in healthy controls." (PMID 36250055, 2022). "Therefore, PLCG1 and NLRC4 may mediate the development of sepsis." (PMID 36250055, 2022). "Compared to that of healthy individuals, the expression level of AIM2, CASP4, NLRC4, and PYCARD was significantly upregulated, while the expression level of PVJK and PLCG1 was significantly downregulated in both sepsis and septic shock patients." (PMID 36250055, 2022). "The expression of NLRC4, S100A9 and TXN was significantly higher in the sepsis patients." (PMID 40028203, 2025). "We screened a signature featuring three programmed cell death related genes (NLRC4, TXN and S100A9) and found that it could predict the occurrence of sepsis." (PMID 40028203, 2025). "In addition, the expression of CHMP7, NLRC4, and PLCG1 in an in vitro sepsis model was further validated." (PMID 37939116, 2023). "In addition, we found the upregulation of NLRC4 and the downregulation of PLCG1 participated during sepsis progression." (PMID 36250055, 2022). "The results obtained in other kinds of cytosolic PRRs (e.g., NLRP1, AIM2, or NLRC4) were not representative of the entire pathophysiology encountered in sepsis." (PMID 33679687, 2020). "Moreover, the expression of S100A9, NLRC4 and TXN were significantly higher in sepsis group." (PMID 40028203, 2025). "When sepsis evaluation is negative in a neonate with multisystem involvement, alternative considerations include monogenic autoinflammatory disease (e.g., NLRP3/NOMID, NLRC4), primary immunodeficiency, inborn errors of metabolism, and congenital leukemia." (PMID 41477640, 2025).
colorectal cancer (17 papers, 2013 to 2024). A primary or metastatic malignant neoplasm that affects the colon or rectum. "Caspase-1 deficiency has been demonstrated to enhance tumor development in an AOM/DSS-induced colitis-associated colorectal cancer model through the regulation of colonic epithelial cell proliferation and apoptosis that is usually mediated by NLRC4 activity." (PMID 34571825, 2021). "Nlrp3−/−, Nlrp6−/−, Nlrc4−/−, Nlrp1−/−, Nlrx1−/− and Nlrp12−/− mice show increased susceptibility to inflammation-induced colorectal cancer as compared to wild-type mice." (PMID 31186453, 2019). "Caspase-1-deficient or NLRC4-deficient mice show increased colonic epithelial cell proliferation and reduced tumor cell apoptosis resulting in enhanced tumor formation in the colitis-associated colorectal cancer models." (PMID 36932407, 2023). "Here, we show that nucleotide-binding oligomerization domain–like receptor (NLR) family CARD domain–containing 4 (NLRC4) is downregulated in epithelial tumor cells of patients with colorectal cancer (CRC) by using spatial tissue imaging." (PMID 38652550, 2024). "In a model of non-alcoholic fatty liver disease (NAFLD), NLRC4 knockout resulted in increased growth and recurrence of liver metastases from colorectal cancer while significantly limiting hepatic tumor development." (PMID 39456655, 2024). "In a mouse model of non-alcoholic steatohepatitis (NASH), NLRC4 knockout promoted the growth and recurrence of liver metastases of colorectal cancer, but significantly restricted hepatic tumorigenesis." (PMID 37497237, 2023). "In the context of non-alcoholic fatty liver disease, the number and size of colorectal cancer liver metastasis nodes are significantly increased through the activation of NLRC4 in TAMs." (PMID 36932407, 2023). "They reported that NLRC4 promotes tumor-associated macrophages polarization towards the M2 type, increases IL-1 and VEGF production and promotes colorectal cancer metastasis proliferation in the fatty liver." (PMID 36558499, 2022). "Similarly, the NLRC4 inflammasome can also inhibit the occurrence of colorectal cancer by suppressing cell proliferation and promoting cell death." (PMID 37497237, 2023). "Similarly, in a mouse model of colorectal cancer, the expression of Nlrc4 mRNA was diminished." (PMID 37020871, 2023). "Palmitate exposure induces the upregulation of NOD-like receptor C4 (NLRC4), a critical component of the inflammasome complex for IL-1β processing, as well as IL-1β production via TLR4 in tumor-associated macrophages (TAMs) from liver metastases of colorectal cancer." (PMID 31847240, 2019). "Case reports have shown significantly decreased the expression levels of NLRP1, NLRP3, NLRC4, AIM2, and other inflammasomes in patients with colorectal cancer compared to healthy controls." (PMID 38756775, 2024). "They found that the mRNA expression of NLRC3 as an inflammation checkpoint; NLRP1, NLRP3 and NLRC4 as the components of inflammasome and AIM2 were all decreased in colorectal cancer." (PMID 34571825, 2021). "NLRC4-deficient mice with NAFLD also showed decreased tumor-associated macrophages (TAMs) and reduced IL-1β and VEGF expression, highlighting NLRC4’s role in managing the growth and recurrence of liver metastases in the context of both NAFLD and colorectal cancer." (PMID 39456655, 2024). "NLRC4-/- mice with NAFLD also had decreased TAMs and decreased IL-1β and VEGF expression, suggesting that NLRC4 plays a key role in the growth and recurrence of liver metastases in the context of both NAFLD and colorectal cancer." (PMID 37497237, 2023).
colorectal cancer (continued). "In multiple colorectal cancer (CRC) patient cohorts, we show that loss of NLRC4 protein expression specifically in the tumor, but not the stroma, is associated with aggressive metastatic progression, decreased patient survival, and lower DC and T cell immune infiltrates." (PMID 38652550, 2024).
enterocolitis (17 papers, 2017 to 2025). An inflammatory process affecting the small intestine and colon. "In contrast, conditional conversion to NLRC4-V341A in adulthood caused systemic autoinflammation with only mild enterocolitis, mirroring AIFEC patients." (PMID 41116055, 2025). "Of note, gain-of-function mutations of NLRC4 result in hyperactivation of the inflammasome and lead to autoinflammation and enterocolitis." (PMID 38607004, 2024). "Heterozygous NLRC4 gain-of-function mutations (OMIM #606831) lead to constitutive activation of the NLRC4 inflammasome resulting in enterocolitis and macrophage activation associated with a clinical picture of HLH." (PMID 32457750, 2020). "Patients carrying the NLRC4 mutation with life-threatening enterocolitis could also benefit from such an antibody specific to IL-18 inhibition." (PMID 38983847, 2024). "However, when rendered hyperactivated by mendelian GOF mutations, NLRC4 induces a spectrum of clinical autoinflammatory syndromes characterized by severe enterocolitis and gut inflammation." (PMID 38652550, 2024). "In particular, patients carrying the NLRC4 mutation with life-threatening enterocolitis could potentially benefit from such an antibody specific to IL-18 inhibition." (PMID 33823154, 2021). "It was reported that the mutation of NLRC4 could cause a syndrome of enterocolitis and autoinflammation." (PMID 34788319, 2021). "In this study, we present a conditional NLRC4 V341A KI mouse model in which pups spontaneously develop severe infantile enterocolitis and autoinflammation." (PMID 41116055, 2025). "Patients with NLRC4 mutations present with early-onset recurrent fever flares, recurrent macrophage associated syndrome (MAS), and/or enterocolitis." (PMID 32737687, 2020). "Furthermore, eicosanoids produced upon NLRC4 inflammasome activation have been shown to contribute to enterocolitis." (PMID 41116055, 2025). "It is speculated that the substitution of phenylalanine for serine at position 171 alters this interaction, thereby phenocopying the effects of the 337 mutation, leading to inflammasome activation and the manifestation of NLRC4-related enterocolitis." (PMID 34276697, 2021). "However, the NLRC4‐inflammasome hyperactivity can impair inflammation resolution and cause diverse auto‐inflammatory diseases, such as the infantile‐onset MAS syndrome and enterocolitis." (PMID 33006196, 2021).
Stroke (15 papers, 2015 to 2025). Sudden impairment of blood flow to a part of the brain due to occlusion or rupture of an artery to the brain. "The work focused on NLRP3 is the most systematic study, followed by NLRP1, NLRP2, and NLRC4 among the inflammasomes associated with stroke." (PMID 34233704, 2021). "We found that NLR family pyrin domain containing 3 (NLRP3) was the most studied, followed by NLRP1, NLRP2, and NLRC4 among the inflammasomes associated with stroke." (PMID 34233704, 2021). "Additionally, other studies have shown that stroke is also associated with NLRP2 and NLRC4 In view of the accelerated progress in elucidating the mechanisms of inflammasomes, their use as therapeutic targets in stroke represents a promising future clinical application." (PMID 34233704, 2021). "In this study, we examined the expression patterns of the AIM2 inflammasome and other cytoplasmic PRRs, including NLRP1a, NLRP3, and NLRC4, in mice after stroke and found that AIM2 and NLRP3 were activated 7 days after cerebral ischemia." (PMID 39854137, 2025). "Here we found a significant increase in the mRNA levels of Tak1 and the inflammasomes Nlrp3, Nlrc4, and Aim2 after stroke compared to sham surgery." (PMID 34628598, 2022). "We detected the expression of three inflammasomes, AIM2, NLRC4, and Caspase-1 using immunofluorescence and found that the expression of the three inflammasomes was significantly decreased in stroke rats after THSWD administration." (PMID 36034843, 2022). "Experimental stroke causes DNA damage, where AIM2 inflammasomes are the main inflammasomes involved in DNA damage, and NLRC4 can form inflammasomes involved in regulating host immune and inflammatory responses." (PMID 36034843, 2022). "We observed DNA damage by gavage of THSWD in stroke rats and assessed the effect of THSWD on AIM2 and NLRC4 inflammasomes vesicles in rat brains after stroke." (PMID 36034843, 2022). "NLRC4 dependent mechanisms can also contribute to brain injury induced by cerebral ischemia, as has recently been described in a rodent‐based model of stroke." (PMID 33006196, 2021). "Moreover, we found that besides NLRP3, other receptors, such as NLRC4, participated in post-stroke inflammasome formation in mice models, which indicates that NLRP3 is not the only path for inflammasome activation." (PMID 33967935, 2021). "In conclusion, the post-ischemic elevation of AIM2 and NLRC4 and their down-regulation by E2 and P may shed more light on the anti-inflammatory effects of both gonadal hormones after stroke." (PMID 32645874, 2020). "In the case of NLRC4, there are limited data regarding its role after a stroke." (PMID 32645874, 2020). "To further verify the mechanism by which 3‐HKA inhibits the activation of the AIM2 inflammasome after stroke, we also examined the mRNA expression of other Nod‐like receptors, such as NLRP3, NLRP1a and NLRC4." (PMID 39854137, 2025). "In the present study, we demonstrated that THSWD attenuated mitochondrial DNA and nuclear DNA damage during stroke; reduced AIM2, NLRC4, and Caspase-1 inflammasomes; and inhibited IL-1β and IL-18 inflammatory factor release after IS." (PMID 36034843, 2022). "By comparison, it was found that the expression levels of AIM2, NLRC4, and Caspase-1 were significantly inhibited in the I/R + THSWD group after the gavage of THSWD to stroke rats." (PMID 36034843, 2022). "TAK1 is reported to regulate the activation of the NLRP3 inflammasome but little is known about the influence of TAK1 on NLRP3, NLRC4, and AIM2 inflammasomes after stroke." (PMID 34628598, 2022). "Next, we investigated the influence of stroke and EPO-administration on the activation of the inflammasomes NLRP3, NLRC4 and AIM2, and their downstreaming cascade." (PMID 34628598, 2022). "Conclusively, we showed that the receptors of NLRP3, NLRC4, and AIM2, the executors of Caspase-1 and−11 were the main contributors of-post stroke inflammasome activation, which participated in the production of IL-1β, IL-18, and GSDMD." (PMID 33967935, 2021).
Stroke (continued). "Instead, NLRC4 and AIM2 along with ASC were suggested to be the major contributors to brain injury in the MCA occlusion (MCAO) model of stroke in mice, as further evidenced by others as well." (PMID 32635451, 2020). "Stroke evoked stronger DAB signals in the vehicle group after 24 h of reperfusion, indicating higher NLRC4 amounts." (PMID 32645874, 2020). "Our results demonstrated that, compared with those in the sham group, the mRNA levels of AIM2 and NLRP3, but not those of NLRP1a and NLRC4, were significantly elevated following stroke." (PMID 39854137, 2025). "Studies have shown that multiple inflammasomes including NLRP3, NLRC4, and apoptosis inhibitor of macrophage 1 (AIM1) among others are active in complex human CNS diseases including Alzheimer’s disease (AD), ALS, multiple sclerosis (MS) and stroke." (PMID 37575265, 2023). "E2 or P selectively mitigated the stroke-induced increase of AIM2 and NLRC4." (PMID 32645874, 2020). "Finally, an expression analysis in the peri‐infarct zone of transient MCAO rats revealed elevated levels of the inflammasome components NLRP1, NLRP3, AIM2, NLRC4, and ASC, consistent with the potential activation of multiple inflammasomes in stroke." (PMID 31015277, 2019). "Although NLRP3 plays a significant role in post-stroke inflammation, there may be some residual protection even in the absence of NLRP3 due to compensatory pathways such as IL- 10/Jak-Stat stabilization and other inflammasomes like AIM2 and NLRC4." (PMID 40272769, 2025). "However, E2 but not P significantly reduced the stroke-dependent enhancement of the NLRC4 protein." (PMID 32645874, 2020). "Vice versa, expression of NLRP3, but not those of NLRC4 and AIM2, was markedly increased in response to recurrent stroke evoked in the contralateral cortex, probably due to the antecedent ischemic stroke as a priming step for NLRP3 inflammasome activation." (PMID 32635451, 2020).
autoinflammatory syndrome (14 papers, 2016 to 2026). A group of disorders of the innate immune system characterized by attacks of seemingly unprovoked inflammation without significant levels of either autoantibodies or autoreactive T cells more characteristic of autoimmune disease. "An independent group identified a similar NLRC4 missense mutation (i.e., V341A) that was associated with infantile enterocolitis, periodic fever, and fatal or near-fatal autoinflammatory syndromes in a family." (PMID 33036374, 2020). "NLRC4, like other NLRs, is involved in a variety of autoinflammatory syndromes via hyperactivating mutations that result in excessive IL-1 family cytokine production." (PMID 33036374, 2020). "Another disease that highly benefits from a targeted approach with monoclonal antibodies against interleukins is the autoinflammatory syndrome due to GOF mutations in the NLRC4 gene (NLR family CARD domain-containing protein 4)." (PMID 31508401, 2019). "The role of NLRC4 in pathology of human diseases has remained unclear until very recently, when gain-of-function mutations in the NLRC4 gene that cosegregate with distinct autoinflammatory syndromes in affected families have been reported." (PMID 27128945, 2016). "For example, autoinflammatory syndromes with gain-of-function mutations in NLRP3 are mainly driven by myeloid-production of IL-1β, while syndromes due to gain-of-function mutations in NLRC4 are associated with epithelial-production of IL-18." (PMID 39468985, 2024). "Recent research has led to novel findings in inflammasome biology and genetics that altered the diagnosis and management of patients with autoinflammatory syndromes caused by NLRP3-, Pyrin-, NLRP1-, and NLRC4-inflammasomes and spurred the development of novel treatments." (PMID 32983099, 2020).